RNF125 (ring finger protein 125)
Diseases named in the same sentence as RNF125 in open-access papers (continued):
Sharing a sentence is not in itself a finding about the gene and the disease.
tumor (7 papers, 2017 to 2025). "A positive association between RNF125 expression and the infiltration of CD4+, CD8+ T cells, and macrophages was observed in tumor tissues from TCGA public database." (PMID 38638430, 2024). "Conversely, when RNF125 was overexpressed in these cell lines, PD-L1 levels decreased, and tumor growth slowed." (PMID 38638430, 2024). "In contrast, overexpression of RNF125 in MC-38 and H22 cells had the opposite effect, resulting in lower PD-L1 levels and delayed tumor growth compared with parental cell lines." (PMID 35965501, 2022). "Once again, the RNF125 gene was significantly downregulated in tumor tissue, and its expression levels were significantly negatively associated with patient prognosis." (PMID 35681566, 2022). "In summary, we identified and validated a new anti-proliferative tumor suppressor gene, RNF125, using transposon mutagenesis screens, comparative genomics, and functional studies." (PMID 35681566, 2022). "Although both cell lines are tumorigenic in transplanted mice, shRNA knockdown of RNF125 significantly accelerated their tumor growth in transplanted mice." (PMID 35681566, 2022). "Further analysis showed that the expression of the RNF125 gene was negatively correlated with clinical staging of tumor." (PMID 35965501, 2022). "First, regarding the functional role of RNF125 as a tumor suppressor, we have only focused on cell proliferation." (PMID 35681566, 2022). "Transfection of a lentiviral RNF125 expression plasmid upregulated RNF125 in Hep3B cells and significantly reduced their tumor growth in vivo." (PMID 35681566, 2022). "First, we confirmed that RNF125 expression was significantly downregulated in tumor tissues compared to paired normal tissue." (PMID 35681566, 2022). "The in vitro results indicated that PD-L1 expression rendered tumor cells more resistant to T cell-mediated cytolysis, whereas RNF125 overexpression resensitized cytolysis killing of T cells." (PMID 35965501, 2022). "Here, we show that one of these genes, RNF125 is a potent anti-proliferative tumor suppressor gene in HCC." (PMID 35681566, 2022). "RNF125 promoting effect on GBC tumor progression was identified to relate with the activation of TGF-β1-SMAD3-ID1 signaling pathway." (PMID 28611292, 2017). "RNF125 was overexpressed, PD-L1 levels decreased, and tumor growth slowed." (PMID 38638430, 2024). "We next examined the mechanism of tumor suppression by RNF125." (PMID 35681566, 2022). "Collectively, our results identify RNF125 as a novel anti-proliferative tumor suppressor in HCC." (PMID 35681566, 2022). "Notably, MC-38 and H22 cell lines with RNF125 knockout exhibited a higher PD-L1 level and significantly faster tumor growth than their parental cell lines." (PMID 35965501, 2022). "Additionally, RNF125 suppressed tumor formation and growth in mice." (PMID 38638430, 2024). "Thus, the analysis showed that the level of RNF125 may be decreasing in the process of tumor occurrence and progression." (PMID 35965501, 2022). "We examined the insertion pattern of transposons in the RNF125 gene in two datasets (Liver-Onc2/HBsAg CISs and Liver-Onc2 CISs) and found that the insertions were scattered throughout the gene and in both transcriptional orientations, suggesting that RNF125 is likely a tumor suppressor." (PMID 35681566, 2022). "For example, the E3 ubiquitin ligase, RNF125, was dramatically downregulated in HCC tumor tissues, and experimental results indicate that RNF125 interacts with SRSF1." (PMID 40129567, 2025). "When RNF125 was knocked out in MC-38 and H22 cell lines, which were then implanted into C57BL/6 mice, an increase in PD-L1 levels and accelerated tumor growth were observed." (PMID 38638430, 2024). "Next, we established of subcutaneous transplanted tumor model in C57BL/6N mice using H22 and MC-38 cell lines with RNF125 knockout (RNF125-KO) or RNF125 overexpression (RNF125-OE)." (PMID 35965501, 2022).
tumor (continued). "In this study, we used a comparative genomics approach to show that one of these CCGs, ring finger protein 125 (RNF125), is an anti-proliferative tumor suppressor in HCC." (PMID 35681566, 2022). "The results showed that RNF125 expression was lower in COAD, LIHC and LUAD tumor tissues than in normal tissues." (PMID 35965501, 2022). "Additionally, contrary to the tumor results of RNF125-OE, reduced expression of CD4, CD8, and F4/80 in RNF125 KO tumors was observed." (PMID 35965501, 2022). "Notably, MC-38 and H22 cell lines with RNF125 knockout, transplanted in C57BL/6 mice, exhibited a higher PD-L1 level and faster tumor growth than their parental cell lines." (PMID 35965501, 2022). "Expression levels of RNF125 in tumor tissues showed a significant negative correlation with patient survival, suggesting that RNF125 plays a crucial tumor suppressive role in human HCC and its inactivation has a significant negative impact on patient survival." (PMID 35681566, 2022). "Two weeks after subcutaneous injection of 1.0 × 106 RNF125-depleted LPCs into the flanks of mice, visible tumors started to form in transplanted mice, while LPCs transduced with negative control (NC) shRNA did not induce tumors, clearly indicating that RNF125 acts as a tumor suppressor." (PMID 35681566, 2022).
RNF125 also shares sentences with these, for which no sentence is quoted: hepatocellular carcinoma (3 papers); acute lymphoblastic leukaemia (1); alcoholism (1); astrocytoma (1); autosomal dominant disease (1); B-cell lymphoma (1); cholangiocarcinoma (1); colon adenocarcinoma (1); colorectal cancer (1); endotoxemia (1); Hypoglycemia (1); influenza (1); Intellectual disability (1); lymph node metastasis (1); Macrocephaly (1); metastasis (1); pancreatic ductal adenocarcinoma (1).